CD14 (CD14 molecule)
Diseases named in the same sentence as CD14 in open-access papers (continued):
Sharing a sentence is not in itself a finding about the gene and the disease.
fungal infection (4 papers, 2016 to 2025). "Our study aimed to understand the impact of BTK inhibition on immune response to fungal infection mediated by macrophages and CD14+ monocytic population obtained from CLL patients." (PMID 32983178, 2020). "Differences in the magnitude of the regulation became apparent for genes such as CD14, which was strongly up-regulated by vitD during both fungal infections." (PMID 28094291, 2017). "Additionally, CD14, TLR1, and TLR2 have been investigated in fungal infection models before." (PMID 40098951, 2025).
idiopathic membranous nephropathy (4 papers, 2018 to 2024). "In the same way, blood circulating CD206-expressing CD14 monocytes are observed in patients with more severe idiopathic membranous nephropathy." (PMID 39845960, 2024). "Patients with early stage of idiopathic membranous nephropathy had higher levels of circulating CD14+/CD163+, CD14+/CD163+/CD206+, and CD14+/CD163+/CD206+/CD115+ macrophages in comparison with healthy controls." (PMID 34307414, 2021).
infertile (4 papers, 2006 to 2021). "No or only negligible expression of hematopoietic and endothelial cell markers (CD14, CD8a, CD15, CD31, CD34, CD45, CD117 and CD133) was detected in MenSCs from healthy volunteers and patients with unexplained infertility." (PMID 34202508, 2021). "Involvement of CD14 during chlamydial infection impedes infection resolution but this does not affect the sequela of infertility as assessed by hydrosalpinx formation." (PMID 16995947, 2006). "The results herein imply that engagement of CD14 in this model does not affect chronic disease progression (e.g. hydrosalpinx formation and by extension, infertility) but does impede resolution of the infection." (PMID 16995947, 2006).
injury (4 papers, 2013 to 2024). Damage inflicted on the body as the direct or indirect result of an external force, with or without disruption of structural continuity. "Although CC16 is known to have anti-inflammatory properties, we have shown recovered TGF-β1 protein expression levels in CD14+ monocytes following treatment with a trauma patient's sera." (PMID 31632392, 2019).
keloid (4 papers, 2019 to 2023). An irregularly shaped, elevated mark on the skin caused by deposits of excessive amounts of collagen during wound healing. "In order to further develop these keloid models, immunocompetent keloid models were created by including CD14+ monocytic cells from peripheral blood." (PMID 37189674, 2023). "Here, we demonstrate that monocyte-derived inflammatory dendritic cells (CD1a+, CD11c+, CD14+) and activated CD4+ T lymphocytes (CD45 RO+) dominated the immune infiltration in keloids while associating with fibroblasts." (PMID 34502327, 2021). "Via MCP-1 expression, the CD14+ monocytes were able to increase fibroblast proliferation and, more importantly, this effect was of a significantly larger magnitude when the CD14+ monocytes were derived from keloid patients." (PMID 31187196, 2019). "CD14+ macrophages derived from keloid tissue, which were co-cultured with CD3+ T-lymphocytes from peripheral blood of keloid patients, were potent stimulators of regulatory T cell differentiation by significantly upregulating Foxp3 expression compared to macrophages from normal skin." (PMID 31187196, 2019). "The results of the image mass spectrometry of an extensive immune panel including 25 markers indicated that CD68, CD14, and CD16 positive macrophages and CD11c-positive DC cells were enriched in keloids, which is consistent with the results of scRNA-seq." (PMID 35990663, 2022). "Furthermore, two modules of macrophages (Module2: highly expresses RNASE1, C1QA, CD163, CD14, C1QC, FCGRT, and MS4A7; Module10: highly expresses APOC1, CTSB, CTSL, and TYROBP), which exhibited the characteristics of TAMs, increased significantly in keloid." (PMID 35990663, 2022).
migraine (4 papers, 2017 to 2025). "In contrast, the percentage of classical monocytes (CD14++CD16−) was 49.9 ± 27.6% in the control group and 72.3. ± 18.1% in the migraine group (p = 0.06)." (PMID 35896985, 2022). "The purpose of the present study was to investigate the role of CD14 in relation to the expression of TNF-α in monocytes, serum levels of TNF-α and MIP-1 Macrophage Inflammatory Protein-1 (MIP-1) in migraine patients during the interictal period." (PMID 28208835, 2017). "Moreover, migraine patients exhibit altered levels of circulating CD14, TNF-α, and MIP-1, with increased serum CD14 concentrations and decreased TNF-α expression in monocytes during the interictal period." (PMID 39407099, 2024). "In summary, we observed that the percentage of peripheral non-classical monocyte (CD14+CD16++) in migraine is lower than in controls, suggesting possible migration of the CD14+CD16++ population into the endothelium of cranial vessels." (PMID 35896985, 2022). "We demonstrated that peripheral blood non-classical monocytes (CD14+CD16++) in migraine patients were lower than controls." (PMID 35896985, 2022). "The aim of the present study was to investigate the levels of circulating CD14 in relation to the expression of tumor necrosis factor alpha (TNF-α) in monocytes, and serum levels of TNF-α and macrophage inflammatory protein-1 (MIP-1) in migraine patients." (PMID 28208835, 2017). "The serum MIP-1 level correlated with Verbal Rating Scale (VRS); the MIP-1:CD14 ratio in monocytes correlated with Visual Analogue Scale (VAS); the MIP-1:CD14 ratio correlated with Migraine Severity (MIGSEV)-Pain scores; and serum CD14 concentration correlated with migraine duration in years." (PMID 28208835, 2017).
monocytopenia (4 papers, 2022 to 2025). "Severe monocytopenia was observed at 1 h after LPS administration, with CD14+CD16− classic monocytes (cMonos) starting to repopulate the blood ~3 h post-LPS and returning to baseline levels (defined as immediately before the LPS challenge) at ~6 h post-LPS16." (PMID 40251340, 2025). "Comparisons with healthy controls confirmed that the patients had profound monocytopenia in both the blood and BM, affecting all monocyte subsets, including classical (CD14+CD16−), intermediate (CD14+CD16+), and non-classical (CD14dimCD16+) monocytes." (PMID 38701783, 2024). "In humans, endotoxin induces a rapid yet transient monocytopenia during the first 2 h after lipopolysaccharide (LPS) injection followed by the sequential reappearance of CD14++CD16− classical monocytes, followed by CD14+CD16+ intermediate cells and finally CD14+ CD16++ non-classical monocytes." (PMID 36926073, 2022).
myocardial inflammation (4 papers, 2014 to 2022). "It has been suggested that the level of CXCL1 was in keep with the extent of myocardial inflammation and the percentage of CD14++DN16− monocytes." (PMID 34781940, 2021). "In contrast, males that had been exposed to plastic caging had significantly increased gene expression of CD11b (p = 0.001), GR1 (p = 0.005), and CD14 (p = 0.006) in the heart during myocarditis using qRT-PCR." (PMID 34445539, 2021). "In contrast, patients with acute myocardial inflammation, TLR4 were more expressed on circulating CD14+CD16+ monocytes than on CD14+CD16- monocytes." (PMID 24499354, 2014).
neutropenia (4 papers, 2015 to 2017). A decrease in the number of neutrophils found in the blood. "Because presepsin derives from CD14, severe neutropenia can cause false-negativity of this molecule." (PMID 28056845, 2017). "Probably the fact that CD14 is expressed in neutrophils or monocytes, might pose a question against its quality, especially in a severe neutropenia after massive chemotherapy." (PMID 28056845, 2017).
non-Hodgkin lymphoma (4 papers, 2015 to 2025). Distinct from Hodgkin lymphoma both morphologically and biologically, non-Hodgkin lymphoma (NHL) is characterized by the absence of Reed-Sternberg cells, can occur at any age, and usually presents as a localized or generalized lymphadenopathy associated with fever and weight loss. "In the case of hematological malignancies, patients with non-Hodgkin’s lymphoma (NHL) exhibit an increase in CD14+ HLA-DRlow-expressing monocytes, which possess immunosuppressive properties, along with elevated levels of CD4+ CD25+ Tregs." (PMID 41303751, 2025). "Using a reverse flow cytometric gating strategy with Lin- selection stain (which includes anti-CD3, -CD19, -CD20, -CD14, -CD16, -CD56 mAbs) Lin-CD34+DNAM-1bright precursor cells could be detected in all the patients with non-Hodgkin Lymphoma, NSCLC and Kaposi Sarcoma." (PMID 38390333, 2024).
nonalcoholic steatohepatitis (4 papers, 2013 to 2023). "In nonalcoholic steatohepatitis, leptin can upregulate CD14 expression through JAK-STAT3 signaling pathway and it has been demonstrated that CD14 can activate CD14-dependent TLR4 pathway to induce an inflammatory response." (PMID 28250578, 2017). "Additionally, given that previous studies have shown that leptin upregulates CD14 in Kupffer cells, and promotes nonalcoholic steatohepatitis (NASH) progression, we examined the expression of leptin after water‐only fasting." (PMID 37929015, 2023). "Recent studies have demonstrated the mechanism of leptin-mediated upregulation of CD14 and TLR4 in nonalcoholic steatohepatitis." (PMID 26484872, 2015). "We previously reported that overexpression of CD14 in Kupffer cells may trigger the progression to nonalcoholic steatohepatitis (NASH) via liver inflammation following hyper-reactivity to low-dose lipopolysaccharide." (PMID 23762319, 2013).
osteonecrosis (4 papers, 2022 to 2025). A none disease characterized by death of bone tissue due to a lack of blood supply. "From a genetic perspective, the authors of study evidenced a correlation between specific immune cell signatures, including CD20%-positive lymphocytes, CD62L-positive monocytes, and CD33br HLA DR+ CD14-cells, and an elevated risk of osteonecrosis." (PMID 39596473, 2024). "Within the absolute count group, monocyte-related immune traits (CD14 − CD16 + monocyte AC, CD14 + CD16 + monocyte AC) have been identified as risk parameters for drug-induced osteonecrosis." (PMID 38654114, 2024). "Yet, features (namely CD14 − CD16 + monocyte, CD14 + CD16 + monocyte, and HLA DR + NK) were positively correlated with drug-induced osteonecrosis." (PMID 38654114, 2024). "Furthermore, miRNAs and TFs targeting CD14, CYBB, NOD2, and TLR1 were predicted and a total of 20 differentially expressed miRNAs were identified in patients with osteonecrosis and controls." (PMID 36193326, 2022).
respiratory infections (4 papers, 2012 to 2024). "Altogether, the clinical phenotype of CD14 deficiency is characterized by respiratory infections, in particular recurrent RSV bronchiolitis, requiring hospital admission." (PMID 35429403, 2022). "SMN signals from individuals with respiratory infections show 3–5x changes, driven largely by the CD14 fraction." (PMID 23226377, 2012). "In Study 6, PBMC subpopulations were dramatically altered at t = 0 h during symptomatic respiratory infection and SMN signal in CD14+ was notably low." (PMID 23226377, 2012). "Furthermore, the broad clinical phenotype of recurrent respiratory infections, and our in vitro TLR data, indicated a central role for CD14 in innate immune signaling that extends beyond TLR4." (PMID 35429403, 2022). "Studies 5 and 6 focusing on SMN levels across timepoints in the same individuals revealed substantial fluctuation in signals and emphasized the impact of respiratory infections on PBMC subpopulations, particularly CD14+ cells involved in innate immunity responses." (PMID 23226377, 2012).
sarcoma (4 papers, 2015 to 2023). A usually aggressive malignant neoplasm of the soft tissue or bone. "We have identified several immune phenotypes that are altered in pediatric sarcomas including elevated CD14+ HLA-DRlo/neg cells, elevated CTLA-4+ T cells, and decreased CD4 T cells." (PMID 26286851, 2015). "Taken together, these data identify an immune profile in sarcoma patients characterized by increased CD14+HLA-DRlo/neg monocytes, total monocytes, and granulocytes." (PMID 26286851, 2015). "Increased CD14+ HLA-DRlo/neg immunosuppressive monocytes were seen in sarcoma patients (p = 0.03); primarily seen in OS." (PMID 26286851, 2015). "Increased tumor necrosis factor receptor II expression was seen on CD14+ cells derived from sarcoma patients as compared to HV (p = 0.01)." (PMID 26286851, 2015). "Increased CD14+HLA-DRlo/neg immunosuppressive monocytes were seen in sarcoma patients as compared to HV (15 % vs. 4 % respectively; p = 0.03)." (PMID 26286851, 2015). "One of the distinguishing immunophenotypes between sarcoma patients in group 1 versus 2 was the levels of CD14+HLA-DRlo/neg monocytes." (PMID 26286851, 2015). "Indeed, the levels of CD14+HLA-DRlo/neg monocytes from all sarcoma patients, in both cell counts (cells/μl) and percentage of total CD14+ monocytes, were positively correlated to the monocyte cell counts." (PMID 26286851, 2015). "This group effect existed because of the preponderance of these cells in OS patients (19 % vs. 4 %; p = 0.01) In addition, increased expression of tumor necrosis factor receptor II was seen on CD14+ monocytes derived from sarcoma patients as compared to HV (p = 0.01)." (PMID 26286851, 2015). "Specifically, in sarcoma, the expression level of SMC4 is significantly correlated with monocyte markers CD14 and CSF1R, TAM marker CD80, and M1 macrophage marker PTGS2." (PMID 36719264, 2023). "The remaining cells were fixed and stained with antibodies specific for sarcoma, vimentin, or white blood cells (WBCs), such as CD45 and CD14." (PMID 31882696, 2019).
scleroderma (4 papers, 2011 to 2024). Scleroderma is a rare autoimmune connective tissue disorder characterized by abnormal hardening of the skin and, sometimes, other organs. "Monocytes appear to be able to differentiate into an endothelial precursor population, and a chimeric cell that is CD68 (+), S-100 (+), and CD14 (−) has been implicated in diseases such as scleroderma." (PMID 21483855, 2011). "CD33dim HLA DR+ CD11b+ Myeloid cell was associated with an increased risk of local scleroderma (OR = 1.161, 95% CI = 1.007–1.339, p = 0.040), and CD14 on Monocytic Myeloid-Derived Suppressor Cells was associated with a decreased risk (OR = 0.895, 95% CI = 0.803–0.997, p = 0.044)." (PMID 39457721, 2024). "When we characterized these cells in terms of ColI and CD34 expression, we found statistically significant differences (P < 0.05) between scleroderma and normal PBMCs in CD11b+/CD14+/ColI+-expressing, CD11b+/CD14+/CD34+/ColI+-expressing and CD11b+/CD14-/CD34+/ColI+-expressing cells." (PMID 21722364, 2011). "Some infiltrated CD14-positive monocytes were colocalized with CEACAM6, indicating that CEACAM6-positive monocytes infiltrated the scleroderma dermis." (PMID 36341379, 2022). "We found that S. epidermidis (moist skin) did not affect local scleroderma via CD14 on Monocytic Myeloid-Derived Suppressor Cells (p = 0.015)." (PMID 39457721, 2024).
Shock (4 papers, 2016 to 2021). The state in which profound and widespread reduction of effective tissue perfusion leads first to reversible, and then if prolonged, to irreversible cellular injury. "Specifically, patients with CD14 rs2569190 GG genotype had increased risk of death related to septic shock, suggesting that CD14 rs2569190 polymorphism may have an important function in the pathogenesis of septic shock." (PMID 29426837, 2018). "We documented the early time course evolution of circulatory Prdx1, hypoxic marker carbonic anhydrase IX, inflammatory cytokines including IL-6, IL-8, IL-10, MCP-1, TNF-α, IL-1β, and danger signaling receptors (TLR4 and CD14) in a cohort of cardiogenic shock patients within 1 day after ECMO support." (PMID 27142532, 2016).
syphilis (4 papers, 2012 to 2024). A contagious bacterial infection caused by the spirochete Treponema pallidum. "Monocytes in early syphilis displayed intermediate type (CD14+CD16+)." (PMID 38694502, 2024). "Instead they raise the possibility that the syphilis spirochete could be affecting macrophage-DC progenitor cells in the bone marrow, before they differentiate into CD14+ monocytes and mobilize into the blood stream." (PMID 22816000, 2012). "Our data illuminate that the monocyte immunophenotype in early syphilis is characterized by an abundance of intermediate (CD14+CD16+) and non-classical (CD14−CD16+) monocytes, while late syphilis is marked by classical (CD14+CD16−) monocytes." (PMID 38694502, 2024).
vasculitis (4 papers, 2020 to 2025). "In conclusion, the C3-C3b-iC3b axis is activated already in the early vasculitis lesion leading to progressive accumulation of CD11b+ and CD14+ cells." (PMID 35747245, 2022). "The pathogenetic role of CD11b+ and CD14+ cells in immunocomplex-mediated vasculitis is unclear." (PMID 35747245, 2022). "MIF and matrix metalloproteinase 9 (MMP9), which is known to control the access of monocytes and T cells to the vascular wall, are increased in both diseases, while CD14 is involved in the activation of monocytes and neutrophils in PR3-ANCA vasculitis." (PMID 33023023, 2020). "In PR3-ANCA vasculitis, levels of TNF-α, thromboxane A2 (TXA2) and CD14 were increased, while in MPO-ANCA vasculitis the C-C motif chemokine receptor 8 (CCR8) levels was higher and IL-10 expression was lower compared to controls." (PMID 33023023, 2020). "The study also observed various cellular communication patterns of vasculitis at different time points and identified co-expression modules related to ribosomal function, cell proliferation, and immune responses in CD19+ B cells, CD4+ T cells, CD8+ T cells, CD14+ monocytes, and CD16+ monocytes." (PMID 40207219, 2025).
viral hepatitis (4 papers, 2018 to 2022). An acute or chronic inflammation of the liver parenchyma caused by viruses. "Also, the number of CD14+CD68+ Kupffer cells is increased in patients with viral hepatitis in another study." (PMID 29854831, 2018). "However, the role of MafB in modulation of CD14+ monocytes in chronic viral hepatitis was not fully elucidated." (PMID 31447817, 2019).
visceral leishmaniasis (4 papers, 2013 to 2025). A severe form of leishmaniasis characterized by irregular bouts of fever, substantial weight loss, swelling of the spleen and liver, and anemia (which may be serious). "In cases of visceral leishmaniasis caused by L. infantum, elevated CD14 expression has been reported, indicating a strong inflammatory response and suggesting active infection." (PMID 40100809, 2025). "Based on observational data, it has been proposed that plasma IL-6 and IL-8, IFN-γ, IL-27, and soluble CD14 are the major mediators of the pathogenicity of kala-azar." (PMID 40732663, 2025). "Macrophages resident in the liver (Kupffer cells) are reservoirs of the intracellular amastigote form in visceral leishmaniasis, characterized by the expression of characteristic macrophage markers (F4/80, CD14, CD68, CD11b)." (PMID 38966642, 2024). "In canine visceral leishmaniasis, peripheral monocytes TLR2+/CD11b+/CD14+ and hepatic macrophages CD11b+/CD18+ seem to be associated with lower tissue parasite load." (PMID 23668673, 2013).
acute kidney injury (3 papers, 2020 to 2022). Sudden and sustained deterioration of the kidney function characterized by decreased glomerular filtration rate, increased serum creatinine or oliguria. "Therefore, blocking CD14, required for several TLRs signaling, can inhibit NGAL overexpression and prevent trauma related acute kidney injury (TRAKI)." (PMID 36059503, 2022).